ERBB2 (erb-b2 receptor tyrosine kinase 2)
Diseases named in the same sentence as ERBB2 in open-access papers (continued):
Sharing a sentence is not in itself a finding about the gene and the disease.
breast cancer (continued). "After ERBB2 dimerization is induced, these structures proliferate and invade, much like breast cancer lesions in patients." (PMID 27998284, 2016). "As to the breast cancer, high ERRα expression has been found to correlate with poor clinical outcome and/or unfavorable biomarkers such as ErbB2." (PMID 26871469, 2016). "Although it is approved for use in combination with capecitabine or letrozole for treating ErbB2-positive breast cancer, adjuvant lapatinib as a single agent for women with early-stage ErbB2-positive breast cancer shows marginal efficacy." (PMID 27286447, 2016). "We have previously demonstrated that alcohol stimulated the migration/invasion in breast cancer cells over-expressing ErbB2." (PMID 27416801, 2016). "Regulated by Erb-B2 receptor tyrosine kinase 2 and insulin, induce a metabolic shift in breast cancer cells." (PMID 27551267, 2016). "We further compared six other breast cancer cell lines for the expression of ErbB2/p38γ MAPK and CSC population." (PMID 27416801, 2016). "More importantly, p38γ MAPK siRNA significantly inhibited an alcohol-induced increase in CSC population, mammosphere formation and migration/invasion of breast cancer cells overexpressing ErbB2." (PMID 27416801, 2016). "Consistent with this, trastuzumab plus pertuzumab plus 3E10 results in greater in vitro and in vivo antitumor activity in ErbB2-overexpressing breast tumor models, suggesting its potential use for treating ErbB2-overexpressing breast cancer." (PMID 26999718, 2016). "Some non-overlapping mechanisms of resistance to trastuzumab and lapatinib likely exist in erbB2-positive breast cancers, as lapatinib has been approved by the FDA to treat erbB2-positive MBC that has progressed on trastuzumab-based therapy." (PMID 26621843, 2016). "Alcohol exposure stimulated the phosphorylation of p38γ MAPK (p-p38γ) which was co-localized with phosphorylated ErbB2 and CSCs in the mammary tumor tissues." (PMID 27416801, 2016). "Our data indicate the existence of a multiprotein complex consisting of ERM proteins, Ebp50, Hsp90, ErbB2 and ErbB3 in breast cancer cells." (PMID 27029001, 2016). "FISH is also used clinically to detect other chromosomal aberrations in solid and hematological cancers, such as amplifications of the ERBB2 locus in breast cancer, to aid diagnosis or as a prognostic marker." (PMID 27507988, 2016). "ErbB2 overexpression is a highly validated target for monoclonal antibody therapy in breast cancer in both the adjuvant and metastatic setting." (PMID 27597943, 2016). "Various parameters representing gene and chromosome copy numbers were evaluated for association with pCR in an effort to identify parameters most effective for improving prediction in the neoadjuvant treatment of ERBB2-positive breast cancer." (PMID 27576528, 2016). "The involvement of calpain-1 in regulation of TZ sensitivity and survival pathway by regulating cleavage and activity of ERBB2 in breast cancers has been recently investigated." (PMID 27863425, 2016). "On the contrary, tumors initiated by other mechanisms, such as ERBB2-driven breast cancer, pancreatic cancer, and glioblastoma, appear to be less susceptible to BET inhibitors as monotherapy." (PMID 27259270, 2016). "Trastuzumab is a humanized immunoglobulin G1 (IgG1) monoclonal antibody targeting the Her2/neu receptor, recommended to treat the ErbB2 positive breast cancer, as monotherapy or in combination with other chemotherapy for adjuvant or palliative treatment." (PMID 27051190, 2016). "Substantiating this, overexpression or knockdown of IRS1 or IRS2 in MMTV-ErbB2 mammary cancer cell lines had little effect upon ErbB2 signaling." (PMID 27765041, 2016). "It has been shown that the Cre-mediated deletion of 14-3-3σ in an erbB2-driven breast cancer mouse model enhances tumor initiation and metastases." (PMID 27409835, 2016).
breast cancer (continued). "In mammary epithelial cells, PTPD2 (PTPN14) is connected to erb-b2 receptor tyrosine kinase 2 (ERBB2) signaling, of which ERBB2 has been shown to be overexpressed or amplified in a portion of breast cancers and plays a role in tumorigenesis." (PMID 27240404, 2016). "In these studies we also found ERBB2/HER2, a member of epidermal growth factor receptor family which is overexpressed in about 10% of the ER+ breast cancers phosphorylated and activated by JAK2 induced by PRL through PRLR." (PMID 27564112, 2016). "In the breast cancer animal model Wip1 overexpression significantly accelerated mammary gland tumor formation MMTV- Erbb2/MMTV-Wip1 mice." (PMID 26883196, 2016). "In the future, we will examine additional genes such as MYC, KRAS, and ERBB2 in breast cancer and other cancers." (PMID 27846853, 2016). "Nearly 30% of total breast cancer patients overexpress human epidermal growth factor receptor 2 (ErbB2 or HER2)." (PMID 26918448, 2016). "In breast cancer cells, ErbB2, an orphan receptor, is frequently overexpressed and forms a heterodimer with a kinase dead counterpart receptor, ErbB3." (PMID 27531070, 2016). "ErbB2 signalling, which is amplified by EphA2 binding, is an important therapeutic target for breast cancer." (PMID 27619642, 2016). "Breast cancer patients are subtyped based on the estrogen receptor (ER), progesterone receptor (PR), and/or ERBB2 (HER2) status of the tumor." (PMID 27472462, 2016). "Clinically actionable mutations in BRCA1, BRCA2 and ERBB2(HER2) were detected in 5.5% of patients, while 53% had genomic alterations matching ongoing or concluded breast cancer studies." (PMID 27901097, 2016). "In ERα-positive T47-D and MCF-7 human breast cancer cells, overexpression of ERβ not only attenuated Akt signaling via down-regulation of ErbB2/ErbB3 but also improved the sensitivity of these cancer cells to tamoxifen." (PMID 27669218, 2016). "Results from the oncogenetic tree model indicate that ErbB2 copy number variation is the frequent early event of human breast cancer." (PMID 27190992, 2016). "Several studies have also found that activation of Src causes lapatinib resistance, more specifically activated Src is upregulated in β1-integrin- and mTORC1-mediated resistance to lapatinib in erbB2-positive breast cancer cells." (PMID 26621843, 2016). "Although most of these studies involved breast cancer with EGFR or ERBB2 overexpression, some researchers have conducted studies on the other HER family genes, including ERBB4." (PMID 26907936, 2016). "Given the emerging evidence for interaction between EGFR/ErbB2 and IGF/IRS signaling in breast cancer, we investigated crosstalk between ErbB2 and IRSs." (PMID 27765041, 2016). "It specifically inhibits the growth of breast cancer cell lines addicted to ErbB2, inducing cell cycle arrest in the G1 phase." (PMID 27255951, 2016). "The main limitation of such approach is the rarity of ERBB2 and ERBB3 activating mutations among breast cancers." (PMID 27602491, 2016). "In breast cancer, the tumor-metastasis discrepancy rates are 9–18% for estrogen receptor (ER), 24–31% for progesterone receptor (PR), and ~10% for ERBB2." (PMID 27028851, 2016). "Double transgenic mice originated by crossing MMTV-p130Cas and MMTV-NeuT mice, which express the oncogenic form of the rat neu gene, homologous to human ErbB2, showed an accelerated onset of mammary tumor formation." (PMID 26716506, 2016). "What is the down-stream signaling of ErbB2 responsible for alcohol-enhanced aggressiveness of mammary tumors?" (PMID 27416801, 2016).
breast cancer (continued). "ERBB2 overexpression is found in 15-20 % of breast cancers and defines a unique subtype of breast cancer." (PMID 26907936, 2016). "At the gene levels, genes with recurrent amplifications in breast cancer showed different degrees of concordance: 100% for ERBB2 and FGFR1, 96% for CCND1, but 88% for MYC, suggesting possible differences for driver genes." (PMID 27028851, 2016). "Our findings demonstrate that alcohol affects CSC in breast cancer cells overexpressing ErbB2 much more than cells with low ErbB2." (PMID 27416801, 2016). "With respect to upstream regulation, integrin β4 is essential for ErbB2-mediated breast carcinogenesis and progression and for P-cadherin-triggered stem cell and invasive properties in basal-like breast cancer cells." (PMID 26845172, 2016). "In breast cancer, ERBB4plays an important role in the survival of ERBB2+ cells after they acquire resistance to lapatinib and trastuzumab." (PMID 27270314, 2016). "HER2/ERBB2 amplification/overexpression determines the eligibility of breast cancer patients to HER2-targeted therapy." (PMID 27716627, 2016). "The three main classical subtypes are defined by expression of the oestrogen receptor (ER), progesterone receptor (PR; ERPR positive breast cancer) and the epidermal growth factor receptor ErbB2/Her2 (Her2 positive)." (PMID 26725330, 2016). "Consistently, in human ErbB2 positive breast cancers that develop resistance to trastuzumab, p130Cas expression is significantly increased suggesting that elevated levels of p130Cas can be involved in trastuzumab resistance." (PMID 26716506, 2016). "In 15–25 % of human breast cancers the HER2 receptor, encoded by the proto-oncogene ERBB2 is amplified." (PMID 27491866, 2016). "A series of n=29 formalin-fixed paraffin-embedded breast cancers were subjected to ERBB2 copy number assessment by fluorescence in situ hybridization (FISH, Vysis, Abbott)." (PMID 27716627, 2016). "The targets of the top luminal miRNAs were activators of EMT (ZEB1, ZEB2) and basal subtype transcription (IL-6, EGFR, STAT3), whereas the targets of the top basal miRNAs were involved in adipogenesis pathways and luminal breast cancer (ERBB2, ERBB3)." (PMID 27845906, 2016). "In breast cancer cell lines, high expression of ErbB2 and p-p38γ MAPK was generally correlated with more CSC population." (PMID 27416801, 2016). "It should be noted that our studies were performed in the presence of overexpressed ErbB2 which was developed to mimic the amplification seen in human breast cancer." (PMID 27765041, 2016). "ERBB2 is typically amplified in tumors and overexpressed in breast cancer, and ERBBs are very important in cancer studies." (PMID 27535739, 2016). "For instance, a potential role in suppression of malignant melanoma has been described for PLXNB1, while cooperation with ERBB2 and a pro-metastatic role was reported for breast cancer cells." (PMID 27215396, 2016). "Ligand binding to ErbB3 in SKBR3 breast cancer cell membranes leads to formation of large ErbB3 clusters with modest levels of co-localized ErbB2; this indicates that domain reorganization can occur during signaling." (PMID 27570763, 2016). "OA has previously been shown to activate the EGFR in a ligand-independent manner, and also to downregulate the expression of ERBB2 in breast cancer cells." (PMID 27894086, 2016). "Up to 44 % of all breast cancer subtypes bear PI3K pathway aberrations such as PIK3CA, PIK3R1, AKT1, and PTEN mutations, in particular luminal A (53.4 %) and ERBB2-enriched (47 %) subtypes, although much less common in the basal-like (10 %) subtype." (PMID 27590516, 2016). "Here we demonstrate that lowering p130Cas expression in breast cancer cells is sufficient to induce ErbB2 degradation by autophagy." (PMID 26716506, 2016). "Lapatinib has been approved for treatment of ErbB2-positive breast cancer and for other cancers that overexpress ErbB2." (PMID 27441659, 2016).
breast cancer (continued). "In SUM149 triple negative breast cancer cells and in BT474 ERBB2+ breast cancer cells expression of an activated form of STAT3; an activated form of AKT; or an activated form of MEK1 inhibited the lethality of [ruxolitinib + MMF] treatment (p < 0.05)." (PMID 26981780, 2016). "According to previous research, overexpression of EGFR, ERBB2, and ERBB3 is associated with poor prognosis and negatively correlated with estrogen receptor (ER) expression in breast cancer." (PMID 26907936, 2016). "The HER2/ERBB2 (erb-b2 receptor tyrosine kinase 2) proto-oncogene is activated by overexpression/amplification in 15% of breast cancers (BCs)." (PMID 27716627, 2016). "We identified circRNAs specific to breast tumor samples and catalogued circRNAs unique to each of the three breast cancer subtypes: triple negative (TN), estrogen receptor positive (ER+), and ErbB2 overexpressed–HER2 positive (HER2+)." (PMID 27829232, 2016). "Collectively, these results show that TOM1L1 is an important element of an ERBB2-driven proteolytic invasive programme and that TOM1L1 amplification potentially enhances the metastatic progression of ERBB2-positive breast cancers." (PMID 26899482, 2016). "In particular, amplification and overexpression of ErbB2 and ErbB3 have been correlated to poor prognosis for breast cancer patients." (PMID 27029001, 2016). "In breast cancer, incomplete surgical resection of tumor is responsible for ERBB2 overexpression in cancer cells, resulting in stimulation of growth and poorer prognosis." (PMID 26820579, 2016). "Breast cancer patients which are ERBB2 positive (30 % of patients) can be treated with the medication trastuzumab, with the trade name Herceptin." (PMID 27112211, 2016). "It was recently demonstrated that treatment of ErbB2 positive SKBR3 and BT474 breast cancer cell lines with proteasome inhibitor causes a 50% downregulation of ErbB2 protein expression, indicating that ErbB2 degradation is proteasome independent." (PMID 26716506, 2016). "EGFR mutation or ErbB2 overexpression has been viewed as critical biomarkers for treatment of EGFR TKIs in NSCLC and breast cancer patients." (PMID 26595522, 2016). "Alcohol exposure caused a drastic increase in CSC population and mammosphere formation in breast cancer cells overexpressing ErbB2/HER2." (PMID 27416801, 2016). "Similar results were observed in BT474 cells, a breast cancer cell line naturally expressing high levels of ErbB2." (PMID 27416801, 2016). "Alcohol preferentially increases CSC population, mammosphere formation and migration/invasion in breast cancer cells overexpressing ErbB2." (PMID 27416801, 2016). "Several basal miRNAs (miR-125b, miR-142, miR-152, miR-146b, miR-222, and miR-212) have also been predicted to target luminal factors that have been previously identified in breast cancer, including ERBB2, ERBB3, ERBB4, and FOXA1." (PMID 27845906, 2016). "Breast cancer is a molecularly heterogeneous disease that comprises five major subtypes (luminal A and B, ERBB2, basal and normal-like) with different clinical characteristics and prognosis." (PMID 26754771, 2016). "For example, IHC staining intensity and pattern of ErbB2/HER2 is widely used to guide treatment in human breast cancer." (PMID 27441183, 2016). "PGC1α is important for glutamine metabolism in ERBB2‐positive breast cancer and glutamine transporters are proposed therapeutic targets in melanoma, highlighting the therapeutic potential of this metabolic pathway." (PMID 26365896, 2016). "Overexpression of ErbB1 and/or ErbB2 occurs in many types of human cancer, such as breast cancer, colon cancer, head and neck cancer, and lung cancer." (PMID 27286447, 2016). "To further explore the specificity of Trast-NGs, we compared the extent of growth inhibition (MTT dye incorporation) of ErbB2-overexpressing (BT-474) vs. ErbB2-low (MCF-7) breast cancer cell lines by DOX encapsulated within control IgG-NGs vs. Trast-NG." (PMID 26859680, 2016).
breast cancer (continued). "ERBB2-amplified breast cancers have been since isolated as a molecular subgroup representing about 15% of invasive breast cancers, usually of high tumor grade and exhibiting a poor survival." (PMID 27602491, 2016). "p38γ MAPK is downstream of ErbB2 and ErbB2/p38γ signaling pathway and it plays an important role in alcohol-induced aggressiveness of breast cancer cells." (PMID 27416801, 2016). "Here we demonstrate that in breast cancer cells overexpressing ErbB2, p130Cas protects ErbB2 from autophagy-mediated degradation by interfering with its ubiquitination." (PMID 26716506, 2016). "A recent report has identified the non-receptor tyrosine kinase Src as a crucial mediator of trastuzumab resistance in erbB2-positive breast cancers." (PMID 26621843, 2016). "p38γ MAPK is downstream of ErbB2 and plays an important role in alcohol-enhanced aggressiveness of breast cancer." (PMID 27416801, 2016). "In breast cancer, the ErbB2-ErbB3 signaling dimer was shown to be essential for tumor formation and maintenance." (PMID 27447549, 2016). "Lapatinib is generally reserved for the late-stage treatment, and only in combination with capecitabine for ErbB2-positive breast cancer in women, whose cancer has progressed following previous chemotherapy with anthracycline, taxanes, and trastuzumab." (PMID 27596216, 2016). "While ERBB2 expression is well correlated with poor breast cancer prognosis, similar studies in gastric cancer (GC) have been inconsistent." (PMID 26955870, 2016). "It is well known that breast cancer is highly heterogeneous and can be divided into four major subtypes based on gene expression profiling: luminal A, luminal B, ErbB2, and basal-like." (PMID 26595523, 2016). "The correlation between pERM levels and ErbB2 levels shown in SKBR3 cells was also observed in MCF7 breast cancer cells, after treatment with NSC668394." (PMID 27029001, 2016). "For example, while ErbB2 overexpression in breast cancer is a strong predictor of poor disease prognosis, ErbB2 overexpression accompanied by ErbB1 expression is associated with worse prognosis." (PMID 27286447, 2016). "In breast cancer cells, when the p130Cas adaptor protein is depleted, ERBB2 becomes ubiquitinated by c-cbl and degraded via autophagy." (PMID 27863425, 2016). "The data indicated that t-DARPP expression was up-regulated in trastuzumab-resistant ERBB2-positive breast cancer cells." (PMID 26872373, 2016). "A variety of genes, including PIK3CA, PTEN, TOP2A and MET are candidate markers for prognosis and response to treatment in ERBB2-positive breast cancer." (PMID 27576528, 2016). "In particular, HSP90 inhibition facilitated the intracellular delivery of TZ-conjugated nanoparticles (ANPs), carrying the chemotherapeutic drug doxorubicin, into ERBB2+ breast cancer cells, resulting in improved antitumor activity." (PMID 27863425, 2016). "This revealed several known kinase targets in breast cancer such as ERBB2, PAK1, RPS6KB1 and PTK2 (refs 16, 17), together with a new candidate kinase target, TLK2." (PMID 27694828, 2016). "Deletion of the GAT domain (ΔGAT mutant) abolished TOM1L1 pro-invasive activity in SKBR3 cells and in HCC-1954 cells (another ERBB2+/ER+/TOM1L1− breast cancer cell line)." (PMID 26899482, 2016). "To further assess the involvement of p130Cas in clinical resistance to trastuzumab, we evaluated the correlation between p130Cas expression and failure to trastuzumab-based therapy in ErbB2 positive breast cancer patients." (PMID 26716506, 2016). "For example, the short-term alcohol exposure stimulates the migration/invasion of breast cancer cells expressing high levels of ErbB2/HER2." (PMID 26655092, 2016). "We next investigated TOM1L1 role in breast cancer by manipulating its expression level in ERBB2+/ER+/TOM1L1− SKBR3 cells (by overexpression) and in ERBB2+/ER+/TOM1L1+ BT-474 cells (by short interfering RNA (shRNA)-mediated silencing)." (PMID 26899482, 2016).